ENSG00000306206 (novel transcript)
Gene: Long non-coding RNA gene on chromosome 20 (4,023,670 to 4,041,744, reverse strand). Ensembl gene ENSG00000306206.
Gene Ontology:
Biological process: response to iron ion